DNMT3A (DNA methyltransferase 3 alpha)
Diseases named in the same sentence as DNMT3A in open-access papers (continued):
Sharing a sentence is not in itself a finding about the gene and the disease.
leukemia (continued). "Emerging data indicate that the DNMTs, including DNMT1, DNMT3a, and DNMT3b, which catalyze promoter methylation, are upregulated in leukemia." (PMID 26673819, 2016). "Studies performed in mice with conditional knockout of Dnmt3a revealed a role for DNA methylation in mediating the self-renewal and differentiation of normal hematopoietic stem cells and leukemia stem cells." (PMID 27999265, 2016). "It is worth noting that NCL expression also positively associates with the levels of DNMT3A and DNMT3B in leukemia patients." (PMID 25015109, 2014). "In the Dnmt3a-null HSCs, an extremely large number of hypomethylated genes were found that are commonly overexpressed in different types of leukemia, including AML and ALL." (PMID 23946816, 2013). "Interestingly, in a mouse model of chronic lymphocytic leukemia (CLL) where B1a cells are the leukemia cell of origin, Dnmt3a depletion resulted in the activation of NOTCH signaling and Dnmt3a-deficient CLL cells were sensitive to NOTCH signaling inhibition." (PMID 39537978, 2025). "Overexpression of DNMT1 and DNMT3a, coupled with suppression of MS and TET1, may drive the aberrant epigenetic modifications associated with leukemia development." (PMID 41254398, 2025). "The heterozygous combination of FLT3ITD, TET2, and DNMT3A leads to aggressive leukemia." (PMID 39078434, 2025). "To assess how exactly the enhanced oligomerization of DNMT3A hotspot mutant may affect DNMT3A’s function such as chromatin targeting, we turned to the TF-1 leukemia cell model." (PMID 38600075, 2024). "To further assess the ability of DNMT3A-corrected cells to initiate leukemia, we determined the leukemia-initiating cell (LIC) frequency from two patient samples by performing limiting dilution transplantation assays with re-mutated or corrected leukemic blasts." (PMID 39553934, 2024). "Although the role of mutant DNMT3A in leukemia development remains unclear, one hypothesis proposes that mutant DNMT3A has a dominant negative effect over wild-type DNMT3A." (PMID 38696033, 2024). "DNMT3A mutations are frequently observed in aging individuals without overt leukemia and in association with clonal hematopoiesis of undetermined potential (CHIP)." (PMID 37509445, 2023). "In particular, serial transplantation assays of Dnmt3a null cells did not lead to overt malignancy, suggesting that transformation into leukemia requires sequential mutations." (PMID 38028538, 2023). "DNMT3A as a clonal hematopoiesis of undetermined potential (CHIP) mutation is not considered a high-risk mutation per the ELN 2022 leukemia classification, and it responds optimally to standard therapy with long term complete remission and cure." (PMID 36831522, 2023). "3.1.d—Mutation in NPM1, FLT3 and DNMT3A AML with three-way interaction among NPM1, DNMT3A and FLT3 occurs in around 6% of AML and is characterized by high leukemia stem cell (LSC) frequency, aberrant immunophenotype (with low CD34 and high CD56) and overexpression of hepatic leukemia factor (HLF)." (PMID 36831522, 2023). "As a modular part of our nanocarrier system, siRNA can be designed and synthetized against any oncogenic factor and we here propose a targeted siRNA-transport system composed of an anti-CD33-antibody, protamine and siRNA that efficiently targets the leukemia-related oncogenes DNMT3A and FLT3." (PMID 36457063, 2022). "Moreover, oncogene knockdown of DNMT3A leads to increased survival of mice carrying leukemia patient-derived xenografts." (PMID 36457063, 2022).
leukemia (continued). "Clonal hematopoiesis of indeterminate potential (CHIP) in leukemia associated genes including DNMT3A, ASXL1, TET2 with a variant allele frequency (VAF) of ≥2% can confer a predisposition for hematological malignancy including overt leukemia, as well as thrombosis, stroke and cardiovascular events." (PMID 34639121, 2021). "Similar to SPOP, intact DNMT3A has been found to be critical for PML-RARA-driven leukemia 41,42." (PMID 33531470, 2021). "In addition, high-dose anthracycline therapies show certain efficacy for DNMT3A mutant leukemia in AML clinical trials, while the increased toxicity limits its application." (PMID 34663800, 2021). "The co-occurrence of mutations in DNMT3A, NPM1 and FLT3-ITD is the most frequent combination of mutations found in AML, which highlights the synergy of this complex gene interaction in causing leukemia." (PMID 32545659, 2020). "Given the promising results in murine leukemia models with co-occurring mutations, we then evaluated the ex vivo activity of TP-0903 and TKIs in human primary samples with coexisting recurrent mutations (e.g., FLT3-ITD, IDH1/2, ASXL1, DNMT3A, NPM1, and SRSF2)." (PMID 33268594, 2020). "However, DNMT3A mutations showed high prevalence in leukemia patients, with 20% in AML and 10% in myelodysplastic syndrome (MDS), which led to further investigation of the role of DNMT3A in hematopoiesis." (PMID 31527484, 2019). "Besides DNMT3a and DNMT3b, leukemia-derived microvesicles also increased the protein and mRNA levels of AICDA (activation-induced cytidine deaminase) in recipient cells." (PMID 31752198, 2019). "Moreover, in case of lung cancer and leukaemia this interaction of miR29b with DNMT3A, DNMT3B and SP1 has already been proved." (PMID 30496316, 2018). "AML patients often have complete loss of DNMT3A enzyme activity, but its role when only partially inhibited and in combination with a second driver mutation of leukemia is not known." (PMID 29464054, 2018). "In contrast, the variant allele frequencies of DNMT3A and other concurrent mutations were relative stationary or even decreased during follow-up in the patients without leukemia transformation." (PMID 29619119, 2018). "In addition to its tumor suppressor role in leukemia, DNMT3A also mediates stem‐like cell expansion in ovarian cancers." (PMID 28179359, 2017). "For example, DNMT3A mutant leukemia cells may undergo leukemic extramedullary infiltration in NOD/SCID mice, a result partially linked to high expression levels of TWIST1, an epithelial-mesenchymal transition (EMT) inducer." (PMID 28127428, 2017). "This study also proposed that miR-143 may play a major role in leukemia-cell proliferation and apoptosis, probably by silencing of DNMT3A." (PMID 28890884, 2017). "Somatic mutations of several epigenetic modulators (DNMT3A, TET2, IDH1/2) occur frequently among patients with pre-leukemia diseases such as MDS and apparently healthy individuals with clonal hematopoiesis or CHIP, an aging-related phenotype associated with increased risk of AML." (PMID 29075615, 2017). "The DNA methyltransferase Dnmt3a suppresses tumorigenesis in models of leukemia and lung cancer." (PMID 28425913, 2017). "While single mutations in DNMT3A do not evolve into leukaemia or alter levels of methylation, complete knockdown of DNMT3A in murine models is seen to produce cellular properties such as inhibited differentiation." (PMID 28286768, 2017). "One recent study in murine HSC has indicated that many genes deregulated in leukemia, including transcription factors, exist in sites termed methylation canyons that are prone to methylation loss in the absence of DNMT3A." (PMID 27597933, 2016). "Consistent with previous reports, we observed that AML patients showed significantly increased DNMT3A mRNA level than healthy volunteers, which indicated that high DNMT3A expression might contribute to the pathogenesis of leukemia." (PMID 27528035, 2016).
leukemia (continued). "Altogether, our findings show that DNMT3A mutation does not participate to relapse or leukemia progression during our period of clinical follow up." (PMID 26486081, 2015). "We previously found that long-term exposure of leukemia cells to imatinib induces expression of DNA methyltransferase 3A (DNMT3A) and EZH2, which then interact with one another and suppress the expression of phosphatase and tensin homolog deleted on chromosome ten (PTEN) in leukemia cells." (PMID 25955299, 2015). "Importantly, no cases of donor cell leukemia were observed in recipients of grafts with only DNMT3A mutations." (PMID 41458386, 2025). "Notably, such DNMT3A-mutated pre-leukemic cells were found in patients whose bulk leukemia cells also carried NPM1 and FLT3-ITD mutations, implying DNMT3A lesions arose earlier and persisted after the transient remission of the NPM1/FLT3-ITD-mutant leukemic clone." (PMID 40651916, 2025). "Another study suggested that DNMT3A-mutated donor clones may enhance graft-versus-leukemia effects, particularly in the absence of post-transplant cyclophosphamide (PTCy), contributing to lower relapse rates and improved progression-free survival." (PMID 41458386, 2025). "While certain mutations (e.g., DNMT3A, TET2, and ASXL1) are frequently observed in clonal hematopoiesis and seem to occur relatively early in leukemogenesis, others tend to emerge later during the progression of leukemia, they include mutations in FLT3, NRAS, and RUNX1." (PMID 37958832, 2023). "Unlike the mutations associated with clonal hematopoiesis (e.g., DNMT3A, TET2, SF3B1 etc.), NMP1mut acts as a “gate-keeper” mutation contributing to leukemogenesis, and acquisition of these mutations appears to be a “first hit” in the development of overt leukemia." (PMID 36831522, 2023). "In the ELN 2022 leukemia classification, DNMT3A is not considered a high-risk mutation." (PMID 37509445, 2023). "Importantly, expression of the most frequently mutated genes in T cell lymphoma or leukemia (i.e., DNMT3A, TET2, JAK, NOTCH1, CDKN2A, PTEN, and FBXW7) was not altered in miR-H18-BCMA CAR T cells." (PMID 35821635, 2022). "Furthermore, IDH1+ and IDH2+ leukemias differ in their mutational profiles, with high incidence of DNA (cytosine-5)-methyltransferase 3A (DNMT3A) mutations reported in IDH1+, but not IDH2-R140+ AML38,43." (PMID 33976256, 2021). "Therefore, necroptosis may play an important role in DNMT3A-mutant leukemia and serve as a potential therapeutic target." (PMID 34663800, 2021). "CHIP is driven by somatic mutations in leukaemia driver genes, such as Janus Kinase 2 (JAK2), Tet methylcytosine dioxygenase 2 (TET2), ASXL Transcriptional Regulator 1 (ASXL1) and DNA (cytosine-5)-methyltransferase 3A (DNMT3A), leading to reduced diversity of the blood pool." (PMID 32526214, 2020). "However, the biological functions of DNMT3A mutation in KMT2A-PTD-positive leukemia cells have not been studied before." (PMID 32015320, 2020). "As recent discoveries provide similar evidence that the deprived serine/glutamine metabolic pathway is lethal for the growth of leukemia cells, we believed that the altered cellular metabolic and increased anti-oxidative stress capabilities might be characteristic for DNMT3A R882 mutant clones." (PMID 28418922, 2017). "Recent works have shown that the absence of Dnmt3a or Tet2 in hematopoietic stem cells predisposes to leukemia formation, but that restoring the expression of Dnmt3a after the leukemia had developed did not revert the phenotype." (PMID 28425913, 2017). "However, whether miR-196b is required for leukemia initiation and development by somatic DNMT3A loss-of-function mutations is not known." (PMID 39580581, 2025).
leukemia (continued). "However, ALPK1 expression was also increased in individuals without DNMT3A mutations, suggesting that activated TIFAsomes may involve other leukaemia driver mutations." (PMID 40269158, 2025). "To dynamically monitor ST2+ Treg cells in malignant BM niches, we developed two aggressive leukemic models: MLL-AF9eGFP and DNMT3A/FLT3ITD, and confirmed in both the increases of KLRG1+ST2+ Treg cells in the BM TME with the progression of leukemia." (PMID 40691440, 2025). "On the other hand, the treatment with the DNMT3A and FLT3-siRNA nanocarriers reduced the percentage of circulating hCD45-positive leukemia cells, which was compared on day 12 after treatment." (PMID 36457063, 2022). "We substantiated the results of the in vitro-treatment of primary patient cells with three additional patient leukemia cells, patient #805 (DNTM3A- and FLT3-ITD-mutant), patient #770 (only DNMT3A-mutant) and #719 (FLT3-ITD)." (PMID 36457063, 2022). "To assess the role of these enzymes in the methylation of CAT promoter in leukemia cells, first we characterized DNMT1, DNMT3A, TET1-3 mRNA expression levels in CLL and HD B cells." (PMID 36112236, 2022). "In line with this tumor suppressive role of DNMT3A, a recent study also reported upregulation of DNMT3A in AML patients, correlating with a better leukemia-free and OS." (PMID 36059621, 2022). "These leukemias were highly enriched in NPM1, and particularly in composed NPM1/DNMT3A mutants, but NPM1 status alone was insufficient to explain the existence of the FLT3-like pattern." (PMID 33592069, 2021). "Surprisingly, high potency against both the two tested leukemia cell lines was displayed also by 4a (IC50 values = 0.5 (U937) and 0.3 (HL60) μM), which showed a drop of inhibition potency against DNMT3A." (PMID 32075099, 2020). "Indeed, PU.1/DNMT3A/DNMT3B interactions may be favored by high amounts of PU.1 in leukemia." (PMID 29449903, 2018). "Recent work has demonstrated that Dnmt3a deletion in HSC, promotes self-renewal and expansion of the LT-HSC pool, resulting in leukemia with incomplete penetrance and prolonged time to disease development." (PMID 27636998, 2016). "When microvesicles were treated with RNase, the level of DNMT3a, DNMT3b, and AICDA decreased, indicating that leukemia-derived microvesicles influence the methylation status of recipient cells via transmission of microvesicular RNA." (PMID 26582468, 2015). "By analyzing the GEO datasets, we found that NCL levels are in parallel with the expression of DNMT1, DNMT3A and DNMT3B in leukemia patients." (PMID 25015109, 2014). "More recently, mutations in DNMT3A, but not NPM1, were identified in pre-leukaemic HSCs from patients with double DNMT3A/NPM1 mutant AML, further supporting the leukaemia-initiating pedigree of mutant DNMT3A." (PMID 25056697, 2014). "Further evaluation revealed that these compounds were more potent against human DNMT3A than against human DNMT1 and induced the re-expression of a reporter gene, controlled by a methylated cytomegalovirus (CMV) promoter, in leukemia KG-1 cells." (PMID 24678024, 2014). "Dnmt3a−/− HSCs show increased H3K79 methylation relative to Dnmt3awt HSCs, with the most significant increase in the DNA methylation canyon, a region highly enriched for genes dysregulated in leukemia." (PMID 39078434, 2025).
leukemia (continued). "Imatinib may have potential applications in prostate cancer treatment, as it can induce resistance by recruiting DNMT3A and EZH2 to the promoter region of PTEN in leukemia patients, thereby downregulating the transcription of this gene." (PMID 39309810, 2024). "It has been suggested that increased expression of maintenance DNA methyltransferases (DNMTs) or de novo expression of specific DNMTs (e.g., DNMT3A and DNMT3B) contribute to the development of leukemia by inducing aberrant hypermethylation of important genomic regions." (PMID 38731939, 2024). "DNMT3A, found increasingly in aging populations without overt leukemia, is a driver gene which precedes NMP1mut, providing a self-renewal advantage to the leukemic clones." (PMID 36831522, 2023). "To further investigate whether the enhanced receptor interactions could affect anti-leukemia efficacy of GDYO against DNMT3A-mutant AML cells, we compared the anti-leukemia efficacies against OCI-AML3 of bare GDYO, GDYOB and GDYOM in serum-free media." (PMID 36163326, 2022). "Persistence of somatic mutations occurring in the DNMT3A, TET2 and ASXL1 genes was found to be indicative of a state of CH rather than residual leukemia post-therapy." (PMID 34771594, 2021). "For example, mutations in DNMT3A are often acquired early in AML evolution, but are not sufficient to develop leukemia." (PMID 34771594, 2021). "Mice expressing Shp2D61Y do not usually succumb to leukemia until 45 weeks after induction of expression and mice with Dnmt3a haploinsufficiency do not develop disease until approximately 80 weeks." (PMID 29464054, 2018). "Our results indicate that, in the absence of mixed lineage leukemia fusions, an alternative pathway for engaging an oncogenic MEIS1-dependent transcriptional program can be mediated by DNMT3A mutations." (PMID 26434589, 2016). "By contrast, all other tested somatic mutations detected in tumor-infiltrating leukocytes, including in known leukemia genes (DNMT3A, TET2, and BCOR) were not identified in breast cancer cells consistent with their origin in the leukocyte component." (PMID 28721364, 2015). "In some cases, DepMap fails to identify genes that are known to be essential for leukemia survival, such as DNMT3A or histone deacetylases; however, these false negatives are due to redundant paralogs that prevent cellular effects when only one paralog is deleted." (PMID 41279954, 2025). "The altered expression of DNMTs, encoding DNMTs (DNMT1, DNMT3a, and DNMT3B) could result in global changes of methylation in leukemia cells and breast cancer stem-like cells, while DNMT1, DNMT3A, and DNMT3B are all upregulated in most cancer types (8, 6, and 9, respectively) in this study." (PMID 31828117, 2019).